GMIP (GEM interacting protein)
Description:
Stimulates, in vitro and in vivo, the GTPase activity of RhoA.
Synonyms: ARHGAP46
Tractability: Antibody: its Gene Ontology location is reachable by antibodies, with high confidence. PROTAC: ubiquitination databases record sites on it; its protein half-life has been measured.
Gene: Protein-coding gene on chromosome 19 (19,629,473 to 19,643,657, reverse strand). Ensembl gene ENSG00000089639.
Subcellular location (Human Protein Atlas): Cytosol; Nucleoplasm; Plasma membrane
Pathways (Reactome):
Signal Transduction: CDC42 GTPase cycle; RAC1 GTPase cycle; RHOA GTPase cycle
Gene Ontology:
Molecular function: GTPase activator activity; protein binding
Biological process: small GTPase-mediated signal transduction; intracellular signal transduction; negative regulation of small GTPase mediated signal transduction; regulation of small GTPase mediated signal transduction; signal transduction
Cellular component: cytosol; nucleoplasm
Genetic constraint (gnomAD): Loss-of-function variants: 51 observed, 93.37 expected, observed/expected ratio (o/e) 0.55, 90% interval 0.44 to 0.69. The upper end of that interval is the gene's LOEUF score, 0.69, which puts it in group 2 of 6, group 1 being the genes least tolerant of losing a copy. Missense variants: 1,073 observed, 1,228.4 expected, observed/expected ratio (o/e) 0.87, 90% interval 0.83 to 0.92. Synonymous variants: 523 observed, 528.31 expected, observed/expected ratio (o/e) 0.99, 90% interval 0.92 to 1.06.
Homologues: Orthologues: chimpanzee GMIP (99% identical), macaque GMIP (97% identical), dog GMIP (88% identical), pig GMIP (86% identical), mouse Gmip (82% identical), rat Gmip (81% identical), guinea pig GMIP (80% identical), rabbit GMIP (78% identical), tropical clawed frog gmip (42% identical), zebrafish gmip (34% identical), Caenorhabditis elegans spv-1 (19% identical). Paralogues in human: ARHGAP29 (32% identical), ARHGAP45 (30% identical).